CRP (C-reactive protein)
Diseases named in the same sentence as CRP in open-access papers (continued):
Sharing a sentence is not in itself a finding about the gene and the disease.
Stroke (continued). "A national cohort of middle-aged and older Chinese adults showed that participants with elevated levels of both AIP and hs-CRP had the highest risks of stroke (HR: 2.207; 95% CI: 1.771–2.749)." (PMID 41383342, 2025). "elevated serum levels of Hs-CRP and HCY were associated with the risk of developing PSD 1 year after the stroke onset." (PMID 40529498, 2025). "This study has shown that simultaneous elevation of hs-CRP and AIP is significantly associated with an increased overall CVD, particularly stroke." (PMID 40842496, 2025). "A negative correlation was noted between the percentage of CD4+ T cells on D1 and the serum CRP level on D10 after stroke." (PMID 40342517, 2025). "For example, a composite risk model incorporating HRV, CRP, and BNP was proposed, which more accurately predicted complications such as post-stroke infections and delayed neurological deterioration." (PMID 40722730, 2025). "The findings revealed that CRP, especially its monomeric form, plays a significant role in post-stroke brain changes, particularly by promoting or regulating angiogenesis." (PMID 40943152, 2025). "C-Reactive Protein (CRP), Albumin (ALB), fibrinogen, and d-dimer are also closely related to inflammation and have been associated with stroke and mortality in AF patients." (PMID 40073613, 2025). "The current study showed both a highly significant CRP increase compared to 90 days post stroke and a significant correlation between one measure of stroke severity and CRP." (PMID 40447994, 2025). "There was a significant correlation between NIHSS at admission to hospital and CRP at 24 to 120 h after stroke onset." (PMID 40447994, 2025). "Among stroke-related factors, infections in the acute phase and/or elevated CRP at Day 1 had the most impact on the models by attenuating several of the RRRs and their significance, but all p-values remained < 0.05." (PMID 41315409, 2025). "For instance, the development of specific small-molecule inhibitors (e.g., 1,6-bis(phosphocholine)-hexane) has been shown to impede CRP function and mitigate tissue damage in myocardial infarction and stroke." (PMID 39995674, 2025). "Phase II studies demonstrated that anakinra administered within 6 h of stroke onset was safe and led to reductions in circulating neutrophils, CRP, and IL-6 levels, suggesting systemic anti-inflammatory effects." (PMID 40869247, 2025). "Further evidence linking CRP to neurodegeneration comes from postmortem studies in dementia and AD patients who experienced stroke." (PMID 40943152, 2025). "The largest magnitude of risk was observed for those with a maximal CRP>300 mg/L (MI IRR: 21.54 (9.57 to 48.52); stroke IRR: 6.94 (3.14 to 15.32))." (PMID 40132892, 2025). "C-reactive protein (CRP), an established marker of heightened inflammation, has been associated with CVDs and stroke." (PMID 40076974, 2025). "The percentage of CD8+ T cells positively correlated with CRP levels during the acute and subacute phases of stroke, as well as in the control group." (PMID 40342517, 2025). "Main reasons for exclusion were missing CRP data, a CRP level above 20 mg/L and stroke of other determined or cryptogenic etiology." (PMID 40682467, 2025). "There is a significant relationship between increased CRP and the severity of stable angina pectoris, myocardial infarction, stroke, and coronary artery disease (CAD)." (PMID 41008697, 2025). "Independent factors influencing PIs included age, National Institute of Health Stroke Scale score at the time of admission, activities of daily living scale score at the time of admission, and C-reactive protein level (all p < 0.05)." (PMID 41281550, 2025). "C-reactive protein (CRP), IL-6, 1β and TNF-α expressed by innate immune cells upon inflammation have been associated with myocardial infarction, coronary disease and stroke." (PMID 40255399, 2025).
Stroke (continued). "Carriers of pro-inflammatory alleles exhibit higher CRP and IL-6 levels when consuming high-DII diets and display greater susceptibility to stroke, implying a gene–diet interaction along the diet–inflammation–stroke axis." (PMID 40686813, 2025). "Nevertheless, the percentage of CD8+ T cells in the acute phase (D1) positively correlated with CRP levels during the acute and subacute phases of stroke (D1, D3, D10), as well as in the control group." (PMID 40342517, 2025). "Although cytokine studies have dominated the literature, large-scale cohort investigations demonstrate that elevated CRP and Hcy are independent predictors of early cognitive decline after stroke." (PMID 41268378, 2025). "In adult stroke patients, elevated CRP levels during the acute phase of the disease have been correlated with the extent of brain damage, with higher CRP levels being associated with an unfavorable prognosis." (PMID 41395306, 2025). "Other potential biomarkers suggesting neoplasia as the etiology of stroke are C-reactive protein (CRP) and fibrinogen." (PMID 40584524, 2025). "In patients with coronary artery disease (CAD), robust evidence demonstrated significant risk reductions for CV disorders (n = 3), MACEs (n = 3), revascularisation procedures, stroke incidence, and high-sensitivity C-reactive protein (hs-CRP) levels." (PMID 40547439, 2025). "Among these, 31 studies were focused on all IS subtypes, of which 3 studies looked at PSD/PSCI, 21 looked at all-cause mortality, 12 looked at stroke recurrence, and 6 studies looked at CRP levels." (PMID 41295435, 2025). "Elevated risks of stroke and cerebrovascular events have also been documented, with C-reactive protein (CRP) serving as a potential inflammatory marker." (PMID 41003121, 2025). "Median CRP peaked at 7.0 mg/L 120–144 h after stroke, compared to 0.9 mg/L at follow-up (p-value < 0.01)." (PMID 40447994, 2025). "Mediation analyses identified self‐care ability (assessed via IADL score), nutritional status (BMI and eating disorders), and inflammation factors (CRP) as surrogate mediators in the stroke–sarcopenia relationship." (PMID 40791098, 2025). "A study investigated the relationship between serum CRP levels and the development of depressive symptoms following a stroke." (PMID 40943152, 2025). "The inflammatory mediators produced in periodontal diseases, including IL-6, TNF-α, and C-reactive protein, promote atherogenesis and thromboembolic events, which can contribute to stroke pathogenesis." (PMID 40259824, 2025). "A secondary aim was to investigate in what way the stroke itself seemed to contribute to the elevations of body temperature, CRP and WBC." (PMID 40447994, 2025). "This suggests that hyperuricemia not only directly affects the mortality risk of stroke patients but also partially indirectly influences survival time through SII and CRP." (PMID 40823312, 2025). "High-sensitivity CRP (hs-CRP) assays, commonly used in clinical practice, enable precise detection of CRP levels and serve as valuable predictors of cardiovascular disease and stroke." (PMID 40416687, 2025). "Our findings showed that elevated hs-CRP levels were significantly associated with an increased CVD risk, particularly stroke." (PMID 40842496, 2025). "CRP was slightly elevated during hospitalization compared to 90-day follow up, most significantly at 24–48 and 48-72 h after stroke." (PMID 40447994, 2025). "Among the TOAST stroke subtypes, CRP levels have been documented to be highest in patients with cardioembolic (CE) stroke, followed by those with large artery atherosclerosis (LAA), and lowest in small artery occlusion (SAA)." (PMID 41227149, 2025). "Further evidence supports a consistent association between high CRP levels and poor clinical outcomes in AIS patients, including those undergoing mechanical thrombectomy (MT) and patients with stroke subtypes such as LAA." (PMID 41227149, 2025).
Stroke (continued). "Individuals with probable AD, mixed AD, or major stroke exhibited significantly elevated CRP levels relative to cognitively unimpaired counterparts, with the greatest elevations observed in the mixed AD group." (PMID 40943152, 2025). "For example, numerous studies have shown that ratios such as neutrophil-to-albumin ratio, fibrinogen-to-albumin ratio, C-reactive protein to albumin ratio and High serum lactate dehydrogenase to albumin ratio are closely related to stroke." (PMID 40371078, 2025). "Independent predictors included age, stroke severity, hyperlipidemia, hyperhomocysteinemia, heart failure, CRP, WBC, neutrophil ratio, Hb, FBG, prealbumin, BNP, and serum sodium." (PMID 40529443, 2025). "Although both are related to ischemic stroke, CRP and D-dimer lack the precision to distinguish between stroke subtypes or provide insight into the pathogenesis of ischemic stroke." (PMID 40949500, 2025). "A 2023 study found elevated levels of serum ferritin, CRP, D-dimer, and IL-6 in post-stroke patients: CRP was elevated in 100%, D-dimer in 87%, and ferritin and IL-6 in 60%." (PMID 41362543, 2025). "A total of 572 patients who experienced an ischemic stroke or transient ischemic attack were enrolled, and their serum CRP levels were measured within 48 h of stroke onset." (PMID 40943152, 2025). "Initial interest in the role of CRP in CVD stemmed from early seminal studies that identified baseline CRP as an independent predictor of future myocardial infarction (MI) and stroke in healthy individuals." (PMID 40472800, 2025). "On the other hand, a negative correlation was noted between the percentage of CD4+ T cells on D1 and the serum level of CRP on D10 after stroke." (PMID 40342517, 2025). "In our study, patients with active cancer also had nominally higher levels of CRP compared to controls, which is consistent with previous studies on stroke patients with active cancer." (PMID 39760182, 2025). "Laboratory markers, including glucose (6.45 ± 2.41 mg/dL), TC (1.33 [0.96, 1.90] mmol/L), and hs‐CRP (1.33 [0.68, 2.66] mg/L), were significantly elevated in the stroke group (p < 0.001)." (PMID 41431310, 2025). "For example, elevated levels of C-reactive protein (CRP), a well-established marker of systemic inflammation, have been correlated with increased incidence of myocardial infarction and stroke." (PMID 40733358, 2025). "This study systematically assessed the predictive accuracy of single and combined indicators—CXCL13, WBC, and Hs-CRP—for the rehabilitation outcomes of stroke patients with neurosyphilis by evaluating the AUC." (PMID 40070668, 2025). "Mediation analysis further showed that SII and CRP partially mediated the effect of hyperuricemia on mortality in stroke patients." (PMID 40823312, 2025). "Elevated CRP levels during the acute phase of stroke reflect the extent and severity of cerebral injury." (PMID 39970158, 2025). "This suggests that Hcy and CRP are useful biomarkers for assessing stroke severity and predicting patient prognosis after stent treatment." (PMID 39898976, 2025). "Inflammatory biomarkers, particularly C-reactive protein (CRP) and IL-6, have been independently associated with poor stroke outcomes and reduced HRV." (PMID 40722730, 2025). "Numerous studies have shown a remarkable elevation in IL-6, TNF, CRP, and neutrophils in patients with stroke." (PMID 38699426, 2024). "The same variables screened by stepwise regression and LASSO regression were hematocrit, hs-CRP, NT-probNP, pulse pressure, history of stroke, and d-dimer." (PMID 38228722, 2024). "CRP had significant mediated effects on the associations of METS-IR and UA with stroke risk, and the proportion of mediation was 9.01% and 26.34% respectively (all P < 0.05)." (PMID 39634177, 2024). "According to the present cohort study, a high hs-CRP/HDL-C ratio is a significant risk factor for CVD, new stroke, and heart problems." (PMID 38429790, 2024).
Stroke (continued). "Risk factors included d-dimer, white blood cell count, high-sensitivity C-reactive protein, pulse pressure, history of stroke, hematocrit, and NT-proBNP in the optimal model." (PMID 38228722, 2024). "This marker, along with CRP and homocysteine, was frequently identified as critical in predicting poor outcomes in stroke patients." (PMID 39347249, 2024). "The mechanisms by which CRP contributes to stroke include impairing endothelial function, promoting plaque instability, and activating leukocytes, further exacerbating the inflammatory process." (PMID 39258059, 2024). "Circulating inflammatory and hemostatic biomarkers such as high sensitivity C-reactive protein (CRP), interleukin-6 (IL-6) and fibrinogen are the “usual suspects” and have been consistently associated with risk of CVD and stroke." (PMID 39145154, 2024). "The mediating role of C-reactive protein in the relationship between physical activity, sedentary behavior and stroke in people aged 60 years and over was explored (sedentary behavior and physical activity were continuous variables)." (PMID 39758197, 2024). "This study focuses on the comparison of age, serum HDL, CRP, and serum ferritin levels in ischemic and hemorrhagic stroke patients, providing valuable insights into their roles as biomarkers in stroke prognosis." (PMID 39258059, 2024). "The concomitant increase in endothelin−1 and CRP most likely reflects ischemic lesions post-stroke in order to adapt to the therapy." (PMID 39273236, 2024). "On admission for the fourth stroke, the CRP was 37 mg/L, peaking at 63 mg/L two days after the fever onset." (PMID 39544619, 2024). "Increased platelet activation and inflammatory markers such as C-Reactive Protein (CRP), interleukins, and Von Willebrand Factor (VWF) in AF patients have been shown to be associated with stroke." (PMID 39572434, 2024). "Several observational studies have reported associations of inflammatory biomarkers such as CRP, TNF-α, and Interleukin-6 (IL-6) with PSD/depressive symptoms after stroke." (PMID 37848651, 2024). "High-Sensitivity CRP is a marker of inflammation that predicts incident myocardial infarction, stroke, peripheral arterial disease, and sudden cardiac death." (PMID 38172970, 2024). "Several factors such as older age, atrial fibrillation, pre-stroke smoking, in-hospital visual deficits, in-hospital delirium, pre-hospital mRS and higher in-hospital CRP levels, were found to be independent predictors of mortality five years after stroke." (PMID 37851292, 2024). "In studies in Germany and the UK, CRP has been shown to be an important way to predict heart disease, like myocardial infarction and stroke." (PMID 39247228, 2024). "The positive relationship found in our study between CRP gene expression and the number of days since stroke suggests that inflammatory processes have deleterious effects over time." (PMID 38802847, 2024). "Lastly, the aim of this study was to investigate high-sensitivity C-reactive protein as a potential contributing factor to post-stroke depressive symptoms." (PMID 37848651, 2024). "Increased serum levels of CRP and IL-6 correlate with stroke severity; notably, patients with moderate to severe strokes generally present higher CRP and IL-6 levels." (PMID 38671959, 2024). "Odd ratios (OR) and 95% confidence intervals (95% CI) of stroke according to serum hs-CRP concentrations." (PMID 39247228, 2024). "Inflammatory markers like C-reactive protein (CRP) and interleukin-6 (IL-6) have been associated with stroke severity and outcome." (PMID 39493062, 2024). "Our study revealed that high-sensitivity C-reactive Protein (hsCRP) levels were significantly elevated in stroke patients with LAT." (PMID 39768925, 2024). "The same variables screened by the two methods were hematocrit, WBC, hs-CRP, NT-probNP, pulse pressure, history of stroke, and d-dimer." (PMID 38228722, 2024).
Stroke (continued). "This response was characterized by elevated levels of CRP and total white cell count 18 months post-stroke." (PMID 39634547, 2024). "In recent years, there have been more new biomarkers proposed in stroke, such as CRP, NLR, and RPP, which represent inflammatory and cardiac load markers." (PMID 38911585, 2024). "Moreover, PAC-1+pEVs concentration on D3 positively correlated with stroke lesion volume on D1 (rS = 0.46; p < 0.01), although this association was not significant in the model of multiple regression analysis including age, systolic blood pressure D1, glycemia D1, and CRP D1." (PMID 39457001, 2024). "There was a positive correlation between the days since stroke and salivary CRP gene expression (r = 0.615, p = 0.025)." (PMID 38802847, 2024). "We conducted a final subgroup analysis in stroke patients with hs-CRP levels below 10 mg/L indicating low-grade inflammation." (PMID 37848651, 2024). "The prevalence of residual inflammatory risk (RIR), typically defined by high sensitivity C-reactive protein (hs-CRP) levels ≥2 mg/L has been associated with major cardiovascular events such as myocardial infarction, stroke, and heart failure." (PMID 39401752, 2024). "By using the Student-t test, a p-value for the difference in mean CRP levels between the two stroke types is less than 0.001, indicating that this difference is statistically significant." (PMID 39258059, 2024). "This indicates the linear association between CRP level and the risk of CVD, stroke, and CHD, making CRP a better inflammatory marker for predicting CVD events." (PMID 39742176, 2024). "In this context, inflammatory markers such as neutrophils, lymphocytes, CRP, and IL-6 play an important role in predicting stroke severity as per the NIHSS, disability as per the mRS, poor outcomes according to the BI, and overall mortality." (PMID 38169754, 2024). "The p-value for the difference in mean CRP levels between the two stroke types is less than 0.001, indicating a statistically significant disparity." (PMID 39258059, 2024). "In the current cohort study, our mediation analysis indicated that the relationships between LDH or hs-CRP levels and functional outcomes at 90 days were only partially mediated by stroke recurrence." (PMID 39280700, 2024). "According to this cohort study, a high hs-CRP/HDL-C ratio is a significant risk factor for CVD, new stroke, and heart problems." (PMID 38429790, 2024). "Data shows significantdifference with below and above levels of C-reactive protein among stroke estimated myocardial infarction patients." (PMID 40092874, 2024). "After adjusting for age, stroke severity, TOAST, AF, Hs‐CRP and FBG, we observed an independent association between high level of FAR and poor outcome (adjusted OR, 2.08; 95% CI, 1.28–3.40; p = .003)." (PMID 38376013, 2024). "Further studies are needed to specifically explore the impact of early infections and isolated CRP elevation in the ICU on post-thrombectomy care for stroke patients." (PMID 39150156, 2024). "The mediation models were employed to estimate the potential mediating effects of CRP on the associations of METS-IR and UA with stroke risk." (PMID 39634177, 2024). "Inflammatory markers, such as C-reactive protein (CRP), fibrinogen, and D-dimer, are crucial in understanding the inflammatory response post stroke, which can significantly influence recovery and rehabilitation outcomes." (PMID 38455777, 2024). "Compared with moderate-to-severe stroke, patients with mild stroke have lower hs-CRP levels [2.43 (1.09-5.74) vs. 1.50 (0.69-3.45, P<0.001], and associated with poor functional outcome (OR=3.149, 95% CI=1.669-5.940, P<0.001)." (PMID 36125980, 2023). "C-reactive protein, one of the most-investigated and well-acknowledged inflammatory markers, is reported to be positively associated with SBP within 24 h after stroke onset." (PMID 37508930, 2023).